SIX3 (SIX homeobox 3)
Diseases named in the same sentence as SIX3 in open-access papers (continued):
Sharing a sentence is not in itself a finding about the gene and the disease.
lung adenocarcinoma (7 papers, 2013 to 2021). A carcinoma that arises from the lung and is characterized by the presence of malignant glandular epithelial cells. "Association of SIX3 expression levels with clinical outcomes of patients with lung adenocarcinoma was evaluated using the Kaplan-Meier method and a multivariate Cox proportional hazards regression model." (PMID 23977152, 2013). "SIX3 was down-regulated in lung adenocarcinoma tissues compared to their matched adjacent normal tissues, and this down-regulation was associated with methylation of the SIX3 promoter." (PMID 23977152, 2013). "Overall survival was significantly better in patients with SIX3-high expression group than in those with SIX3 low expression group in all patients with lung adenocarcinomas (p = 0.005), stage I patients (p = 0.008), and patients with BAC features (p = 0.01)." (PMID 23977152, 2013). "SIX3 expression was assessed on 160 NSCLC frozen specimens including 145 lung adenocarcinomas by real-time PCR." (PMID 23977152, 2013). "This study is to assess the expression/function of SIX3 and the significance of SIX3 as a prognostic biomarker in lung adenocarcinoma." (PMID 23977152, 2013). "While in lung adenocarcinoma, SIX3 is downregulated and indicates better prognosis." (PMID 28595628, 2017). "Restoration of SIX3 suppresses cell proliferation and migration of lung adenocarcinoma." (PMID 28595628, 2017). "SIX3 has potential as a novel prognostic biomarker for patients with lung adenocarcinomas." (PMID 23977152, 2013). "SIX3 is a member of the SIX family of homeoproteins that as a DNA-binding transcription factor is downregulated in lung adenocarcinoma tissues and correlated with gender, tumor size, overall survival, and recurrence of patients with lung adenocarcinoma." (PMID 33264103, 2020). "More importantly, we identified SIX3 as prognostic of increased OS and PFS in lung adenocarcinomas." (PMID 23977152, 2013).
glioblastoma (6 papers, 2016 to 2022). The most malignant astrocytic tumor (WHO grade IV). "The TFs found in TR astrocyte, SIX3 has been discovered to suppresses glioblastoma cell growth and invasion via the WNT pathway whereas the TF OVOL1 has been found to participate in EMT in cancers such as breast and colon." (PMID 34976314, 2022). "For SIX3, the tumor suppressor appeared to be hypermethylated in lung cancer and glioblastoma accounting for decreased expression in these cancer types." (PMID 34490256, 2021). "Together, these results indicated that SIX3 silencing induced by the EGFR-ZNF263 signaling axis has a functional role in glioblastoma malignant progression." (PMID 32051553, 2020). "To investigate the function of ZNF263 and SIX3 in the context of glioblastoma development, we first treated the phenotypically normal astrocytes (HEB cells) with high doses of EGF to mimic EGFR/MAPK hyperactivation during tumor initiation." (PMID 32051553, 2020). "In contrast, ZNF263 knockdown, Trametinib treatment, or ectopic expression of SIX3 prevented the tumor-promoting effects of EGFR-vIII on glioblastoma cells." (PMID 32051553, 2020). "By analyzing datasets from TCGA, we found that SIX3 expression was lower in classic subtypes of glioblastoma than other subclasses or normal tissues." (PMID 32051553, 2020). "Here, we firstly showed that EGFR/MAPK hyperactivation results in epigenetic silencing of SIX3 through ZNF263 in glioblastoma." (PMID 32051553, 2020). "We previously showed that SIX3 can be transcriptionally silenced by DNA hypermethylation, functions as a tumor suppressor gene, and inhibits human glioblastoma transcriptionally." (PMID 32051553, 2020). "Treatment cells with DNA methyltransferase inhibitor 5-aza-2′-deoxycytidine reduced DNA methylation of SIX3 promoter and markedly enhanced its expression in glioblastoma cells." (PMID 32051553, 2020). "Intriguingly, Trametinib appeared to specifically reduce ZNF263 protein levels without altering those of KAP1, SUV39H2, EED, or SETDB1, implying that the activation of EGFR/MAPK led to SIX3 silencing in glioblastoma mainly through the regulation of ZNF263." (PMID 32051553, 2020). "SIX3 also inhibits the proliferation and invasion of glioblastoma cells by WNT pathway." (PMID 32051553, 2020). "Thus, both p-EGFR and ZNF263 can be used as an indicator for poor prognosis while SIX3 serves as an indicator for favorable prognosis of glioblastoma." (PMID 32051553, 2020). "Altogether, we conclude that epigenetic silencing of SIX3 is controlled by a sophisticated and highly ordered oncogenic signaling pathway and therefore provide new insights into initiation and progression of glioblastoma." (PMID 32051553, 2020). "Together, our findings demonstrate that epigenetic silencing of SIX3 is controlled by a sophisticated and highly ordered oncogenic signaling pathway and therefore provide new insights into initiation and progression of glioblastoma." (PMID 32051553, 2020). "The effects of ZNF263 on H3K27me3 and H3K9me3 led us to ask whether ZNF263 alter chromatin accessibility of SIX3 promoter in glioblastoma." (PMID 32051553, 2020). "In this study, using the results from Gene Expression Omnibus (GEO) and The Cancer Genome Atlas (TCGA), we analyzed the level of methylation on the CpG island of SIX3 promoter and confirmed our earlier findings that SIX3 is hypermethylated in both low-grade glioma and glioblastoma." (PMID 32051553, 2020). "Because ZNF263 plays a critical role in epigenetic silencing of SIX3 in glioblastoma, we next examined whether erlotinib or Trametinib induced SIX3 expression through the regulation of ZNF263." (PMID 32051553, 2020). "When ZNF263 protein was enriched, it continued to recruit DNMT1/DNMT3A/HMT, induced transcriptional silencing of the SIX homeobox 3 (SIX3) promoter, and triggered or enhanced the oncogenic activity of glioblastoma." (PMID 36091786, 2022).
glioblastoma (continued). "We treated glioblastoma cells with erlotinib, a selective inhibitor of EGFR, which significantly increased SIX3 expression." (PMID 32051553, 2020). "Overexpression of ZNF263 in glioblastoma cells decreased the expression of SIX3, while ZNF263 depletion markedly elevated SIX3 level." (PMID 32051553, 2020). "However, the mechanism underlying SIX3 hypermethylation in glioblastoma is not known." (PMID 32051553, 2020). "We expressed EGFR-vIII in glioblastoma cells, which expectedly increased ZNF263 levels and decreased SIX3 levels." (PMID 32051553, 2020). "Using methylation-specific PCR (MSP) primers, we detected SIX3 DNA methylation in the phenotypically normal astrocyte cell line HEB and three glioblastoma cell lines (U251, U87, and U118), and the level of methylation correlated inversely with the expression of SIX3." (PMID 32051553, 2020). "We treated glioblastoma cells with EGF extrinsically and found that SIX3 was downregulated." (PMID 32051553, 2020).
glioma (6 papers, 2011 to 2021). A benign or malignant brain and spinal cord tumor that arises from glial cells (astrocytes, oligodendrocytes, ependymal cells). "We have previously found that SIX3 is hypermethylated and acts as a suppressor in glioma by transcriptionally repressing AURKA/B." (PMID 32051553, 2020). "We had shown previously that SIX3 promoter contains higher levels of DNA 5-methylcytosine (5mC) in glioma than in normal brain tissues." (PMID 32051553, 2020). "Further data from the same study also indicated that SIX3 down-regulation contributes to glioma invasiveness, this process being strictly related to the activation of Wnt/β-catenin pathway." (PMID 29462960, 2018). "We next examined SIX3 expression in glioma from two independent sets of patients." (PMID 32051553, 2020). "So, it is safe to suppose that IDH1 may affect SIX3 methylation and expression in glioma." (PMID 32051553, 2020). "We first assessed the expression of ZNF263 in HEB cells and six primary patient-derived glioma cells and discovered an inverse relationship between ZNF263 and SIX3." (PMID 32051553, 2020). "The methylation levels of seven gene promoters (ANKDD1A, GAD1, SIX3, SST, PHOX2B, PCDHA8, and HIST1H3E) in glioma patients and cell lines were significantly higher than those in non-tumor controls (p < 0.01)." (PMID 21962230, 2011). "Eight promoter-hypermethylated genes (ANKDD1A, GAD1, HIST1H3E, PCDHA8, PCDHA13, PHOX2B, SIX3, and SST) were confirmed in primary glioma and cell lines." (PMID 21962230, 2011). "Results obtained in a very recent study demonstrated that SIX3 was down-regulated in human glioma tissues and human glioma cells (SHG-44, U251, SF126 and U373-MG) in comparison to normal tissues." (PMID 29462960, 2018). "The GAD1, HIST1H3E, PCDHA8, PCDHA13, SIX3 and SST may regulate the progression of glioma." (PMID 21962230, 2011). "In addition, we found that the percentages of promoter methylation in the ANKDD1A and PHOX2B, but not the GAD1, HIST1H3E, PCDHA8, PCDHA13, SIX3 and SST, were associated negatively with the differentiation degrees of human gliomas." (PMID 21962230, 2011). "The analysis of Repository for Molecular Brain Neoplasia Data (REMBRANT) revealed strong negative correlation between SIX3 and AURKA and between SIX3 and AURKB in glioma." (PMID 28595628, 2017).
Anophthalmia (3 papers, 2010 to 2025). Absence of the globe or eyeball. "Mutations in SIX3 are associated with developmental disorders such as anophthalmia and hypopituitarism." (PMID 41009448, 2025). "Previous research has linked mutations in genes such as CHX10, MAF, PAX6, PAX2, RX (RAX), SHH, SIX3, OTX2, and SOX2 to phenotypes associated with microphthalmia, anophthalmia, and coloboma (MAC)." (PMID 39129019, 2024).
coloboma (3 papers, 2007 to 2024). An abnormality in which a part of a structure in one or both eyes is missing.
diabetes (3 papers, 2018 to 2025). "Nucleotide variants in the locus encoding SIX2 and SIX3 have been linked by GWAS to increased risk for type 2 diabetes (T2D) and diabetes-related traits." (PMID 33893274, 2021). "SIX3 has been implicated as a diabetes risk gene and is important for β-cell function." (PMID 40982369, 2025). "Some research suggest SIX3 linkage to diabetes from genetic studies and show SIX3 as possible regulator of insulin production in β-cells in an age-dependent manner." (PMID 30545422, 2018).
gastric cancer (3 papers, 2021 to 2022). A primary or metastatic malignant neoplasm involving the stomach. "The lncRNA DLGAP1-AS1 has been demonstrated to increase Wnt1 transcription and gastric cancer growth by interacting with Six3." (PMID 35178091, 2022). "In addition, a recent study reported that DLGAP1-AS2 binds to the transcription factor Six3 and inhibits its occupancy in Wnt1 promoter, resulting in the activation of Wnt/β-catenin signaling in gastric cancer cells." (PMID 36376892, 2022).
hypopituitarism (3 papers, 2022 to 2025). A condition of diminution or cessation of secretion of one or more hormones from the anterior pituitary gland. "We identified two children with neonatal hypopituitarism and thin pituitary stalk who were doubly heterozygous for rare, likely deleterious variants in the transcription factors SIX3 and POU1F1." (PMID 35951005, 2023). "The SIX homeobox 3 (SIX3) gene is responsible for the normal development of the pituitary gland in mammals and its genetic variation or absence causes hypopituitarism, suggesting that this gene is a potential candidate for association with growth characteristics in animals." (PMID 35395053, 2022). "Six3 can interact genetically with Hesx1, causing activation of WNT signaling and hypopituitarism associated with pituitary gland dysmorphology." (PMID 35951005, 2023). "To assess the potential for digenic interaction of SIX3 and POU1F1 leading to hypopituitarism, we analyzed Six3+/−; Pou1f1+/dw mice." (PMID 35951005, 2023).
Intellectual disability (3 papers, 2015 to 2023). "The SIX3 p.P74R variant was identified in five individuals with intellectual disability and various other features in four unrelated families, but it was classified as benign because it was also present in unaffected family members (unpublished data, variants and data shared through Mobidetails)." (PMID 35951005, 2023).
neuroblastoma (2 papers, 2006 to 2019). Neuroblastoma (NB) is the most common solid, extracranial childhood tumor. "It is essential for cell survival by modulating mitochondrial responses and has also been associated with neuroblastoma; The SIX3 protein is a transcriptional regulator that plays a role in eye development and is associated with cephalic disorder." (PMID 30898084, 2019).
non-small cell lung carcinoma (2 papers, 2020 to 2021). A group of at least three distinct histological types of lung cancer, including non-small cell squamous cell carcinoma, adenocarcinoma, and large cell carcinoma. "A systematic meta-analysis of non-small cell lung cancer has indicated that higher expression of SIX homeobox 3 (SIX3) is associated with a greater probability of tumorigenesis and a higher TNM stage." (PMID 34604089, 2021). "TRIM27 induces non-small cell lung cancer (NSCLC) cell proliferation and metastasis, and the expression of β-catenin, S100P, TGFB3, and MMP-9 were significantly inhibited by SIX3." (PMID 33264103, 2020).
pancreatic cancer (2 papers, 2016 to 2020). "It suggested that the eight markers: MAPT, SIX3, MIR663, EPB41L3, FAM150A, TRIM73, LOC100128977, and LOC100130148 may serve as potential biomarkers for the early diagnosis of pancreatic cancer." (PMID 33424927, 2020). "However, the multivariate Cox regression analysis indicated that TRIM73, FAM150A, EPB41L3, SIX3, MAPT, LOC100128977, and LOC100130148 might not be independent factors for the prognosis of pancreatic cancer patients." (PMID 33424927, 2020).
Septo-optic dysplasia (2 papers, 2016 to 2020). Septooptic dysplasia (SOD) is a clinically heterogeneous disorder characterized by the classical triad of optic nerve hypoplasia, pituitary hormone abnormalities and midline brain defects. "Importantly, the ventral forebrain deficiencies and optic nerve hypoplasia found in six3a;six3b mutants place Six3 as a potential causative gene in additional congenital diseases involving the forebrain and eyes such as septo-optic dysplasia (SOD) and Kallman syndrome." (PMID 26822689, 2016).
type 2 diabetes (2 papers, 2023 to 2026). "Downregulation of SIX2 and SIX3 alters gene regulatory programs associated with β-cell homeostasis and contributes to type 2 diabetes." (PMID 41892811, 2026). "Genetic variants in or near the CDKAL1, KLF9, GP2, ALDH2, and ITIH4 genes are associated with obesity and genetic variants in or near the GDAP1, PTF1A, SIX3, ALDH2, and PAX4 genes are specifically associated with type 2 diabetes in East Asians." (PMID 37749090, 2023).
alcoholism (1 paper, 2023). "HPE has a heterogeneous etiology, potential causes include maternal diabetes, alcoholism, infections during pregnancy, drugs such as retinoic acid, chromosomal syndromes such as trisomy 13, and recessive autosomal mutations like SHH, SIX3, and ZIC2." (PMID 36845789, 2023).
astrocytoma (1 paper, 2017). "In vivo and in vitro empirical evidence confirmed that SIX3 reversed the malignant phenotype of astrocytoma cells." (PMID 28595628, 2017). "In this study, we further revealed SIX3 as an astrocytoma suppressor gene, which inhibits the tumorigenesis of astrocytoma." (PMID 28595628, 2017). "Three primary human patient-derived astrocytoma lines were cultured, and the expression of SIX3, AURKA, and AURKB was examined." (PMID 28595628, 2017). "Expression of SIX3 in astrocytoma patients correlates with sensitivity to treatment with aurora kinase inhibitors." (PMID 28595628, 2017). "We demonstrate that in astrocytoma, SIX3 acts as a tumor suppressor gene by transcriptionally repressing AURKA and AURKB but does not affect the interaction of AURKA and AURKB." (PMID 28595628, 2017). "SIX3 is a potential biomarker that could be used to predict the response of astrocytoma patients to aurora kinase inhibitors." (PMID 28595628, 2017). "Our previous study showed that the SIX3 gene is hypermethylated, and its expression is decreased in astrocytoma, but the role of SIX3 remains unknown." (PMID 28595628, 2017). "We found that high SIX3 expression in astrocytoma resulted in low sensitivity to aurora kinase inhibitors, and this may partially be due to low expression of AURKA and AURKB." (PMID 28595628, 2017). "Our previous research characterized SIX3 as a hypermethylated gene in astrocytoma." (PMID 28595628, 2017). "We have previously found SIX3 to be hypermethylated in human astrocytoma, but the exact role of SIX3 in astrocytoma tumorigenesis remains unknown." (PMID 28595628, 2017). "SIX3 also notably suppressed the proliferation and invasion of astrocytoma cells." (PMID 28595628, 2017). "Since SIX3 has been confirmed as a negative transcriptional regulator of AURKA and AURKB, we wondered whether SIX3 expression is correlated with the sensitivity of astrocytoma cells to aurora kinase inhibitors." (PMID 28595628, 2017). "A strong inverse correlation between SIX3 and AURKA/AURKB were obtained with normal astrocyte cell line HEB and three astrocytoma cell lines by Western blotting." (PMID 28595628, 2017). "The expression of SIX3, AURKA, and AURKB were further studied in 18 human astrocytoma samples, and both AURKA and AURKB expression showed an inverse relationship with the expression of SIX3." (PMID 28595628, 2017). "SIX3 silencing results in high expression of AURKA and AURKB in astrocytoma." (PMID 28595628, 2017). "SIX3 is a novel negative transcriptional regulator and acts as a tumor suppressor that directly represses the transcription of AURKA and AURKB in astrocytoma." (PMID 28595628, 2017). "SIX3 is identified as a novel negative transcriptional regulator of AURKA and AURKB, and it decreases the expression of AURKA and AURKB in a dose-dependent manner in astrocytoma cells." (PMID 28595628, 2017).
brain tumors (1 paper, 2017). "Though SIX3 is widely expressed in the central nervous system, its role in brain tumors has not been well studied." (PMID 28595628, 2017).
bronchioloalveolar carcinoma (1 paper, 2013). A well or moderately differentiated morphologic variant of lung adenocarcinoma characterized by tumor growth along the alveolar structures without stromal, vascular, or pleural invasion. "Moreover, SIX3 mRNA expression was associated with significantly improved overall survival (OS) and progression-free survival (PFS) in adenocarcinoma patients and patients with bronchioloalveolar carcinoma (BAC) features." (PMID 23977152, 2013).
cleft palate (1 paper, 2020). Cleft palate is a fissure type embryopathy that affects the soft and hard palate to varying degrees. "In hESCs, TCDD-treatment resulted in significant upregulation of LHX4 and SIX3, which are associated with cleft palate, the hallmark phenotype of TCDD toxicity." (PMID 33260776, 2020).